CD96 (CD96 molecule)
Diseases named in the same sentence as CD96 in open-access papers (continued):
Sharing a sentence is not in itself a finding about the gene and the disease.
tumor (continued). "Taken together, our results suggest that CD96 suppresses the cytotoxicity of T cells against a subset of CD155-expressing tumor cell types." (PMID 36672244, 2023). "CD96 was positively related to the number of CD8+ T cells in tumor-infiltrating tissues, suggesting that CD96 is most likely associated with CD8+ T cell dysfunction." (PMID 36674817, 2023). "The current study showed a significantly increased expression of CD96 in the OSCC tumor samples compared to the healthy oral mucosa." (PMID 37046787, 2023). "In vivo inhibition of cancer cell‐intrinsic CD96 enhances the chemotherapeutic response in a patient‐derived tumor xenograft model." (PMID 36581470, 2023). "PD-1, CTLA4, CD96, and TIGIT are associated with each other in tumor immunity, which are candidates for immunotherapy." (PMID 36936375, 2023). "The tumor stroma showed significantly higher CD96 labeling indices compared to the epithelial compartment (pOSCC = 0.047)." (PMID 37046787, 2023). "Studies have shown that the expression of the inhibitory receptor CD96 is also upregulated on tumor NK cells." (PMID 35866671, 2022). "In contrast to delayed tumor progression in TIGIT-/- and CD96-/-, CD226-deficient mice exhibit increased susceptibility to MCA-induced fibrosarcomas as well as metastatic lung colonization (e.g., LLC lung and RM-1 prostate tumors)." (PMID 35812451, 2022). "The mAb exposure of mice treated with anti-CD96 alone was very low for all five mice (A21–25), and tumor volumes were high or medium." (PMID 36140247, 2022). "Various cancers exhibit upregulation of CD155 and corresponding upregulation of NK and T cell expression of TIGIT and CD96 to evade anti-tumor immunity through inducing T cell or NK cell suppression." (PMID 35606854, 2022). "CD96, which is mainly expressed in natural killer (NK) cells and T cells, acts as a vital checkpoint in immunity and tumor progression, with CD96 mice displaying hypersensitive NK-cell responses to immune challenge and significant tumor resistance." (PMID 35223835, 2022). "Tumor stage analysis also exhibited that CD96 expression levels were significantly different between groups in regard to tumor stage." (PMID 36043142, 2022). "Despite short and low exposure, anti-CD96 had a significant and durable effect in combination treatment with anti-PD-1, resulting in increased tumor infiltration of CD8+ T cells and an increased CD8/Treg ratio." (PMID 36140247, 2022). "By blocking CD96 in mice, the growth of primary tumors was inhibited, thus promoting greater tumor control." (PMID 35223835, 2022). "Herein, we showed that CD96 expression on tumor-infiltrating CD8+ T cells is heterogeneous, being expressed on a fraction of PD-1–bright as well as on PD-1–dim T cells." (PMID 35998045, 2022). "It has been shown that a co-blockade of CD96 and PD-1 inhibited tumor growth and lung metastases, and increased local NK-cell infiltration and interferon-γ (IFN-γ) synthesis in several mouse tumor models." (PMID 36140247, 2022). "Blocking CD96 combined with other immune checkpoint inhibitors enhances T cell activity and inhibits tumor growth." (PMID 35769669, 2022). "It has been shown that a co-blockade of anti-PD-1 and anti-CD96 decreases metastases in murine tumor models and results in superior tumor control." (PMID 36140247, 2022). "As an example, following neoadjuvant anti-PD-1 and gemcitabine, adjuvant therapy with anti-CD96 resulted in a significant survival benefit in pancreatic ductal adenocarcinoma (PDAC) tumor-bearing mice." (PMID 35812451, 2022). "Costimulation by anti-CD96 antibodies was effective in countering suppression by Tregs and in inducing the proliferation of tumor-infiltrating T cells (TILs)." (PMID 35998045, 2022). "The increased CD8+ and reduced Treg frequencies resulted in a positive shift of the CD8+/Treg ratio, which importantly has also been described for this tumor model in CD96/PD-1 dual knockout mice." (PMID 36140247, 2022).
tumor (continued). "In order to understand the PK of our mAbs and to predict the concentrations of anti-CD96 and anti-PD-1 in the tumor therapy study, we performed PK studies." (PMID 36140247, 2022). "In order to further corroborate the beneficial effect of the anti-CD96/anti-PD-1 combination, we investigated the composition of tumor-infiltrating lymphocytes in MC-38 tumors after 11 days of treatment." (PMID 36140247, 2022). "To detect the CD96 mRNA and protein expression profiles in human tissues, we evaluated the expression of CD96 in various tumor and normal tissues using the Human Protein Atlas (HPA) database." (PMID 33680972, 2021). "NK cell conversion into intermediate ILC1 or ILC1-like cells in the presence of TGF-β was associated with increased CD96 together with reduced DNAM-1 expression in mouse tumor models, likely driving the observed impairment of the anti-tumor immune response." (PMID 34885076, 2021). "In this report, we assessed the expression of CD96 in 33 different cancer types using the independent Oncomine and TIMER2.0 databases, revealing clear differences of pan-cancer CD96 expression between tumor and normal tissues." (PMID 33680972, 2021). "The expression level of PD-1 and CD96 were increased too in the tumor-infiltrating NK cells compared to NK cells in the surrounding tissues and circulating cells." (PMID 34768814, 2021). "PD-1, TIGIT, and CD96 can negatively affect NK cell function, and targeting these receptors with immune checkpoint inhibitors was found to enhance the anti-tumor response both in vitro and in vivo." (PMID 33572396, 2021). "We adjusted these results based on tumor purity, revealing strong and significant correlations between CD96 and CD8+ T cell markers (CD8A), general T cell markers (CD3D, CD3E, CD2), DC markers (HLA-DPB1, HLA-DRA, HLA-DPA1) in LGG." (PMID 33680972, 2021). "The CD226 activating receptor and the TIGIT and CD96 inhibitory receptors have been shown to be key regulators of anti-tumor immune responses by NK cells." (PMID 34367161, 2021). "On the other hand, CD96 plays an important role in mouse lung metastasis and subcutaneous tumor models." (PMID 34174928, 2021). "And we suppose that CD96 plays a delicate role in tumor initiation or development based on the differential expression profiles." (PMID 33680972, 2021). "A more comprehensive analysis of CD96 profile in human cancer is warranted understand immune-cell-intrinsic effect of CD96 in tumor immunity." (PMID 33680972, 2021). "Paradoxically, an emerging role for CD96 as a negative immune checkpoint was recently proposed, since antibodies targeting CD96 seemed to enhance the anti-tumor potential of CD8+ T-cells in a number of mouse tumor models." (PMID 34122431, 2021). "Engagement of CD226 with its ligands PVRL2 and CD155 on target cells is essential for enhancing the anti-viral and anti-tumor functions of NK cells and T cells, whereas CD96, TIGIT and PVRIG counterbalance CD226-dependent lymphocyte activation." (PMID 34174928, 2021). "Tumor-bearing mice treated with anti-PVRIG mAb showed lower expression of inhibitory receptors CD96 and PD-1 and higher expression of activating receptor NKG2D and cytotoxic molecule TRAIL on tumor-infiltrating NK cells." (PMID 34174928, 2021). "NEFM negatively correlated with PVR (CD155), an immune checkpoint on tumor cells and interacting with CD96, CD226, and TIGIT (T cell immune receptor with immunoglobulin and ITIM domains) on TILs to modulate immune function in tumor microenvironment." (PMID 34001208, 2021). "In vivo blockade of TIGIT or CD96 using Abs inhibited tumor growth and metastasis in an NK cell-dependent manner and thus improved the overall survival in melanoma and experimental or spontaneous lung metastasis models." (PMID 32714324, 2020). "In their study, triple blockade of PD-1, TIGIT, and CD96 significantly inhibited tumor growth in a B16F10 melanoma BALB/c WT mouse model." (PMID 32532329, 2020).
tumor (continued). "Experimental metastases were inhibited in three different tumor models with monoclonal antibody blockade of CD96." (PMID 32117298, 2020). "Numbers of CD96+ NK cells were increased in tumor sites in HCC and exhibited functional exhaustion with decreased of IFN-γ and TNF-α production, low perforin and granzyme B levels, and high IL-10 and TGF-β expression." (PMID 32714324, 2020). "As a promising candidate for immunotherapy, CD96 plays an important role in anti-tumor immune responses." (PMID 32612110, 2020). "Conversely, CD96 was correlated negatively with T cell-mediated immune response to tumor cell (GO:0002842) and T cell-mediated cytotoxicity directed against tumor cell target (GO:0002852)." (PMID 32695752, 2020). "Engagement of CD155 with ligands including CD226 (DNAM-1) and CD96 has been demonstrated to drive anti-tumor immune responses, particularly those by NK cells." (PMID 32532329, 2020). "CD155 and CD112 have been linked to tumor progression and migration in primary tumors and have also been shown to have an immunomodulatory role through interaction with DNAM-1, TIGIT, and CD96 on NK cells." (PMID 32532329, 2020). "Still, in murine models, CD96 was proven to possess a direct inhibitory role of anti-tumor function notably in NK cells." (PMID 32489646, 2020). "Second, we will discuss the expression and function of TIGIT, DNAM-1, and CD96 on lymphoid effector cells as well as tumor cells." (PMID 32489646, 2020). "Compelling evidence confirmed that blocking CD96 enhanced the containment of primary tumor growth in murine model systems in a CD8 + T cell-dependent manner." (PMID 32695752, 2020). "Both TIGIT and CD96 are significantly up-regulated on chronically stimulated tumor-infiltrating NK and T cells, representing markers of exhausted cytotoxic cells." (PMID 32019260, 2020). "Various cancers have shown upregulation of CD155 with corresponding upregulated NK and T cell expression of TIGIT and CD96 in order to evade anti-tumor immunity by eliciting T cell or NK cell inhibition." (PMID 32117298, 2020). "CD96 was earlier found to mediate the adhesion between NK cells and tumor cells to facilitate NK cell cytolysis." (PMID 31552017, 2019). "In HCC patients, the percentage and intensity of CD96 on NK cells, as well as the numbers of CD96+ NK cells, were higher for tumor-infiltrating NK cells compared with NK cells from peri-tumoral tissues." (PMID 31552017, 2019). "Therapeutic blockade of CD96 in tumor metastasis models confirmed its role as a checkpoint receptor on NK cells." (PMID 31552017, 2019). "Like NKG2D, CD226 and CD96 are receptors expressed on the surface of NK cells known to be important for tumour immune surveillance." (PMID 30908480, 2019). "The functional complexities of CD96 in tumour immune surveillance are intriguing, however, they are beyond the scope of this study and we intend to focus on these in further studies." (PMID 30908480, 2019). "Most importantly, a direct inhibitory role of CD96 was proven only for murine NK cells and explored in vivo mainly in the context of tumor models (next paragraph)." (PMID 29868026, 2018). "In contrast to the role of CD96 participating in immune surveillance of tumors, hCD96 itself was identified as tumor marker." (PMID 29868026, 2018). "After three rounds of selection all tested single clones preferentially bound to CD96-positive tumor cells and harboured identical scFvs, indicating that functional v-regions were efficiently enriched." (PMID 22879978, 2012). "The cytolytic properties of the recombinant CD96 mini-antibodies were investigated by chromium release assay with CD96-positive tumor cells and isolated MNC as effector cells." (PMID 22879978, 2012). "Additionally, T-cell cluster 1 exhibited more interactions with other cells through the CD96 signaling pathway and communicated with tumor cells via EPGN." (PMID 41373592, 2025). "TIGIT and CD96 are critical co-inhibitory receptors in tumor immune regulation." (PMID 39911397, 2025).
tumor (continued). "CD96 exhibits dual functionality, with varying effects across different tumor microenvironments." (PMID 40231264, 2025). "CD96 is mainly expressed in T and NK cells and highly expressed in tumor-infiltrating CD8+ T cells." (PMID 39156900, 2024). "Research has indicated that CD47 and CD96 might alter fatty acid oxidation and mediate immune evasion, thereby enhancing tumor radiotherapy resistance." (PMID 38291470, 2024). "Several checkpoint and inhibitory receptors, such as PD-1 (gene name: PDCD1), CTLA4, TIM-3 (HAVCR2), LAG3, CD39 (ENTPD1), CD160, KLRG1, CD96, BTLA, 2B4, and TIGIT, have been implicated in the reduction of immune activity and response in the tumor micro-environment." (PMID 39513882, 2024). "Additionally, platelet-derived TGF-β further enhances tumour metastasis by inhibiting the expression of CD226 and CD96 on NK cell surface, protecting tumour cells from being recognised by NK cells." (PMID 39450176, 2024). "Furthermore, CTLA4 and LAG3 were negatively expressed in tumor-infiltrating lymphocytes, while CD96 and HAVCR2 were highly expressed in cluster CD8_1, indicating functional exhaustion of cells in this cluster within TME." (PMID 37533434, 2023). "The incomplete activation of CD96 downstream signaling cascades may also lead to tumor-promoting effects through activation of MAPK, NF-κB, and PI3K pathways, which contribute to cell proliferation, survival, and migration." (PMID 37741340, 2023). "Thus, we evaluated the expression of CD96 on CSCs in primary tumor cells from human BC samples using flow cytometry." (PMID 36581470, 2023). "Blocking of CD96 signaling could, therefore, also have direct immune-independent effects on tumor cells." (PMID 37046787, 2023). "However, various databases show different levels of CD96 gene expression in tumor and normal tissues." (PMID 36674817, 2023). "However, depending on the histological tumor type, CD96 expression correlates with poorer prognosis or has a protective effect, suggesting that this molecule can exert a complex function depending on the tumor and the immune infiltration." (PMID 37629138, 2023). "Moreover, separate expression analysis of CD96 in the tumor and healthy mucosa epithelium and the tumor and subepithelial stroma was performed." (PMID 37046787, 2023). "Moreover, Src inhibition by dasatinib or tirbanibulin disrupted mammosphere formation in CD96‐overexpressing tumor cells and Stat3 phosphorylation in BCSCs, supporting that CD96 can sustain cancer cell stemness via the Src‐Stat3 pathway." (PMID 36581470, 2023). "CD96 has been previously shown to regulate NK cell function in the tumour microenvironment; however, its role and mechanism at the maternal–foetal interface remains unclear." (PMID 37760110, 2023). "A possible reason for the decreased CD96 expression in the peripheral blood of the OSCC patients could be a shift of CD96-expressing cells from the periphery to the tumor site." (PMID 37046787, 2023). "On the other hand, NK cell’s cytotoxicity against tumor cells expressing CD155 could be improved by disrupting the binding of CD96 to CD155 with a CD96 antibody." (PMID 36674817, 2023). "As a result, the expression of co-stimulatory receptors CD226 and co-inhibitory receptors TIGIT and CD96 on NK cells suggest that CD155 may play a dual role in tumor immunity." (PMID 36674817, 2023). "CD96 expression in tumor tissue and peripheral blood of OSCC patients is differentially regulated." (PMID 37046787, 2023). "A previously unknown role is identified for tumor cell‐intrinsic CD96 and an attractive target in improving the chemotherapeutic response." (PMID 36581470, 2023). "In our study, we sought to address how CD96 could affect the anti-tumor activity of T cells by generating CD96 KO T cells." (PMID 36672244, 2023).
tumor (continued). "Moreover, the CD96 mRNA expression should be correlated with the protein expression in tumor and mucosa specimens, as well as the expression of the immune checkpoints PD1 and PD-L1 and the macrophage markers CD68 and CD163." (PMID 37046787, 2023). "Moreover, the combinatory blockade of PD-1 and CD96 has significantly suppressed tumor growth compared to blocking PD-1 alone." (PMID 37638058, 2023). "To examine how CD96 deficiency in T cells and differential CD111 expression in these tumor cells modulated the cytotoxic capacity of T cells against tumor cells, we co-incubated CD96 WT or KO T cells with luciferase-expressing tumor cells at different E:T ratios for 20 h." (PMID 36672244, 2023). "NK cells in tumor tissue show a higher level of CD96 than those in the peritumoral region." (PMID 37638058, 2023). "This suggests that additional CD96 ligands may be present on tumor cells that mediate CD96 suppression, the identification of which is essential to fully elucidate CD96 function." (PMID 36672244, 2023). "However, there was also some CD96 staining in epithelial tumor cells as well as epithelial cells in the healthy controls." (PMID 37046787, 2023). "CD96 can monitor tumor cells and serve as an indicator of MRD." (PMID 37533738, 2023). "Tumor tissue showed a significant upregulation of CD96 expression." (PMID 37046787, 2023). "In addition, the blocking of CD96 together with PD1 was shown to be efficient against lung metastases in a tumor mouse model." (PMID 37046787, 2023). "The results from preclinical tumor models presented that therapeutic targeting of CD96 and TIGIT has demonstrated significant efficacy and synergistic activity with PD-1 inhibition, which could restore T cell exhaustion to a certain extent." (PMID 37312116, 2023). "The DNAM-1/TIGIT/CD96 pathways offer new ways to improve immune-cell anti-tumor response." (PMID 36059606, 2022). "Moreover, genetic- or biologics-based co-blockade of TIGIT and CD96 has been shown to improve tumor control while co-blockade of TIGIT and PVRIG has also been shown to promote NK cell function." (PMID 35812451, 2022). "This antitumor immune function of CD96 may be derived from the interaction of CD155/CD112 on tumor cells or antigen-presenting cells in the TME with TIGIT/CD96 on CD8 T cells or NK cells, resulting in the inhibition of antitumor NK cells and T cell functions." (PMID 35223835, 2022). "Indeed, patients with higher proportions of tumor-infiltrating CD96+ NK cells and CD155-expressing HCC cells had a worse outcome." (PMID 36011052, 2022). "However, recent findings indicate that CD96 blockade inhibits primary tumor growth in various tumor mouse models, an effect that is dependent on CD8+ T cell activity." (PMID 35164813, 2022). "Therefore, we anticipate that anti-CD96 mAbs remain capable of augmenting Tconv cell responses, in spite of the presence of increasing numbers of Tregs within the tumor microenvironment." (PMID 35998045, 2022). "This anti-PD-1/anti-CD96 combination showed enhanced CD8+ T cell infiltration into the tumor." (PMID 36140247, 2022). "With sufficient plasma levels, the anti-tumor effect of anti-CD96 alone or in combination may potentially be much better than these experiments suggest." (PMID 36140247, 2022). "Overexpression of co-inhibitory receptors (CTLA4, PDL1 and CD96) may promote the increase of depletion of T-cell, thus losing the anti-tumor function in the transmembrane protein 60 high expression group." (PMID 36744183, 2022). "If higher plasma concentrations of anti-CD96 would have been reached, its potential to reduce tumor growth might have been much better." (PMID 36140247, 2022). "However, mice treated with both antibodies showed significantly reduced tumor growth compared to the isotype control or to the anti-CD96 or anti-PD-1 treatment groups." (PMID 36140247, 2022).